CLDN6 (claudin 6)
Diseases named in the same sentence as CLDN6 in open-access papers (continued):
Sharing a sentence is not in itself a finding about the gene and the disease.
breast carcinoma (continued). "Thus, we demonstrated that the downregulation of CLDN6 is regulated through promoter methylation by DNMT1, which depends on the SMAD2 pathway, and that CLDN6 is a key regulator in the SMAD2/DNMT1/CLDN6 pathway to inhibit EMT, migration and invasion of breast cancer cells." (PMID 28867761, 2017). "Previous studies have shown that CLDN2, CLDN6 and CLDN7 are involved in patient response to chemotherapies in cancers including breast cancer and colorectal cancer, yet with no clear mechanism identified." (PMID 38137355, 2023). "Therefore, we speculated that CLDN6 may affect c–MYC by interacting with TAZ, and the mechanism by which CLDN6/TAZ/c–MYC mediated signaling controls glycolysis and proliferation in breast cancer has not been investigated to our knowledge." (PMID 35008557, 2021).
gastric cancer (28 papers, 2013 to 2025). A primary or metastatic malignant neoplasm involving the stomach. "Aberrant expression of the tight junction protein claudin 6 (CLDN6) is a hallmark of gastric cancer progression." (PMID 37762277, 2023). "Both in vitro and in vivo experiments showed that abnormal CLDN6 expression was associated with enhanced proliferation and invasion abilities of gastric cancer." (PMID 31827075, 2019). "Similarly, abnormal expression of CLDN6 has been widely recognized in gastric cancer, in which its expression has been clearly associated with enhanced invasiveness and metastatic properties via well-defined transcription factors." (PMID 37762277, 2023). "Our results suggest that the interaction between YY1 with CREB in AGS cells stimulated with H. pylori LPS is involved in the transcriptional initiation and activation of CLDN6, a perfectly defined tight junction protein associated with enhanced gastric cancer progression and invasiveness." (PMID 37762277, 2023). "Therefore, we explored the proteogenomics changes of gastric cancer tumors associated with claudin-6 expression." (PMID 36430456, 2022). "Because our previous experiments showed that reduced CLDN6 expression affected the invasion ability of gastric cancer cells, we speculated that CLDN6 was closely associated with the process of EMT." (PMID 31827075, 2019). "Some studies have confirmed that CLDN6 expression in gastric cancer tissues is lower than in normal tissues using qPCR, while others have reported CLDN6 as highly expressed in gastric cancer tissues using genetic databases." (PMID 40687428, 2025). "Functionally, CLDN6 knockdown suppresses gastric cancer cell proliferation and invasion, potentially through partial repression of YAP1 and its downstream transcriptional targets." (PMID 40687428, 2025). "CLDN6 expression is significantly upregulated in different types of cancer, including gastric cancer." (PMID 37762277, 2023). "CLDN6 enhances gastric cancer cell proliferation and invasiveness via the YAP1 and YAP1-Snail1 axis." (PMID 35281827, 2022). "Amongst many, abnormal expression of claudin-6 has been recognized as a major promoter of the proliferation and migration of gastric cancer cells." (PMID 36430456, 2022). "Generally, CLDN6 is a tetraspanin transmembrane protein located within the tight junctional complex, in the cell membrane of primary tumors, gastric cancer cells and mouse stem cells." (PMID 36362009, 2022). "Claudin-6 (CLDN6) has been found to be highly upregulated both at the mRNA and protein levels in gastric cancer cell lines and tissues indicating poor prognosis." (PMID 36362947, 2022). "Compared to histologically normal gastric tissues, CLDN6 expression is noticeably reduced in the majority of gastric cancer tissues; however, some have remarkably greater expression levels." (PMID 36620607, 2022). "Dysregulated expression of Cldn6 has been reported in gastric cancer and it has been proposed as a single prognostic marker and tumor-promoting gene of a subset of genomically stable tumors." (PMID 36430456, 2022). "The regulation of MMP2 by CLDN6 and the role of both in cell migration and invasion are demonstrated in gastric cancer cells: CLDN6 increases the activity of MMP-2 to enhance cell migration and invasion by upregulating the expression CLDN1." (PMID 34948213, 2021). "As for proliferation, CLDN6 promotes cell proliferation in human hepatocellular carcinoma, gastric cancer, and endometrial carcinoma." (PMID 35008557, 2021). "In hepatocellular cancer, gastric cancer, endometrial cancer, and ovarian cancer, CLDN6 has the opposite roles." (PMID 34948213, 2021). "In gastric cancer, an OS analysis using the Kaplan–Meier plotter indicates that patients with high CLDN6 expression have a poor prognosis." (PMID 34948213, 2021).
gastric cancer (continued). "In gastric cancer cells, CLDN6 interacted with LATS1/2 and decreased the conversion of LATS into p-LATS, thereby inhibiting the Hippo signaling pathway." (PMID 34948213, 2021). "Bioinformatics analysis has extensively confirmed the prevalence of claudins in gastric cancer patients, especially Claudin-6 and -9, which are considered critical factors related to poor prognosis in gastric cancer." (PMID 39296813, 2021). "In gastric cancer cells, CLDN6 was reported to interact with LATS1/2 and reduce the level of p–YAP, thereby increasing the nuclear YAP activity." (PMID 35008557, 2021). "Overexpression of claudin-6 both in gastric cancer cells and in vivo models results in increased migration, proliferation, and invasiveness." (PMID 34822542, 2021). "Abnormal expression of CLDN6 was also observed in tissue obtained from patients with gastric cancer." (PMID 34822542, 2021). "Our in vitro and in vivo experimental results revealed that the abnormal expression of CLDN6 was related to the proliferation and invasion abilities of gastric cancer." (PMID 31827075, 2019). "CLDN6 expression in gastric cancer tissues was also significantly higher than adjacent normal tissues, and showed a similar pattern in the GEO datasets GSE26942 and GSE54129." (PMID 31827075, 2019). "The colony formation and CCK8 assays revealed that the proliferative ability of gastric cancer cells was inhibited after suppression of CLDN6 expression." (PMID 31827075, 2019). "In this study, we found that the expression of CLDN6 mRNA and protein was upregulated in gastric cancer cell lines and tissues, which indicated poor prognosis." (PMID 31827075, 2019). "Immunohistochemical staining for CLDN6 expression was performed on tissue microarray of 494 gastric cancer samples from Renji hospital." (PMID 31827075, 2019). "In the present study, we found that CLDN6 was significantly upregulated in gastric cancer, and its abnormal increased expression often predicted poor prognosis of GC patients." (PMID 31827075, 2019). "CLDN1, 2, 6, 9, 16, and 19 were found to be of significance in gastric cancer in the tight junction family, and CLDN6 expression was the highest." (PMID 31827075, 2019). "In summary, the present study found the pro-tumorigenic effect of CLDN6 in gastric cancer and revealed that CLDN6 promoted YAP1 nuclear translocation by reducing YAP1 phosphorylation, thereby activating downstream oncogenes." (PMID 31827075, 2019). "The GSE110875 dataset contained 80 gastric cancer samples, which were divided into low and high CLDN6 expression groups." (PMID 31827075, 2019). "Wound healing and transwell assays showed that the migration ability of gastric cancer cells significantly decreased upon CLDN6 knockdown." (PMID 31827075, 2019). "In this study, we found that claudin 6 is highly expressed in gastric cancer, especially in a cell and tissue type specific manner with high malignancy potential." (PMID 31827075, 2019). "On the other hand, claudin-6 overexpression in the human gastric cancer cell line AGS increases its invasion, migration, and proliferation potentials." (PMID 24009024, 2013). "Positive expression of claudin-6 protein was found in 55.0% (22/40) of gastric cancer tissues and in 78.6% (22/28) of adjacent tissues." (PMID 23919729, 2013). "The positive expression rates of claudin-6 in gastric cancer tissues and adjacent tissues were 55% and 79% respectively (P = 0.045 < 0.05)." (PMID 23919729, 2013). "However, in our present work the cytoplasmic staining of claudin-11 was strong in gastric cancer tissues and weak in adjacent tissues, reveals that claudin-11 may be a positive diagnostic marker in gastric cancer which was different with claudin-2 and claudin-6." (PMID 23919729, 2013). "The expression rate of claudin-6 in gastric cancer tissues was lower than the rate in adjacent tissues (The Chi-square test/Chi-Square Goodness-of-Fit Test, P =0.045 < 0.05)." (PMID 23919729, 2013).
gastric cancer (continued). "On the contrary, in the present study we found that claudin-6 protein wan expressed at low levels in gastric carcinoma tissues but highly expressed in histologically normal adjacent tissues." (PMID 23919729, 2013). "Additionally, although we primarily focused on CLDN6 as a target for the imaging and treatment of EC, CLDN6 is upregulated in many common cancers, such as ovarian, breast, and gastric cancers." (PMID 39915118, 2025). "CLDN6 is expressed in pluripotent stem cells and fetal tissues but repressed in most adult tissues, whereas CLDN6 is overexpressed in 54–100% of germ cell tumors, 14–55% of ovarian cancers, 17–21% of endometrial cancers, 10–52% of gastric cancers and 6–11% of NSCLCs." (PMID 41164107, 2025). "However, CLDN6 acts as a tumor promoter to increase cell proliferation of human hepatocellular carcinoma cells and gastric cancer." (PMID 36362009, 2022). "We identified key pathways and driver genes that can be used as novel prognostic markers and identified genes with very high connectivity in the genetic interaction network, the so-called hub genes, and transcription factors that can become therapeutic targets for Cldn6 expressing gastric cancers." (PMID 36430456, 2022). "Expression of CLDN6 indicates poor prognosis of gastric cancer." (PMID 36339684, 2022). "In addition, increased expressions of claudin 6, 7, or 9 are able to enhance the migration, invasion, and proliferation of gastric cancer cells." (PMID 36010553, 2022). "However, in gastric cancer tissues and cell lines, the expression of CLDN6 protein was up-regulated and an increased CLDN6 level was associated with enhanced proliferation and invasion abilities of gastric cancer." (PMID 36362009, 2022). "CLDN6 also acts as a tumor promoter to increase cell proliferation in gastric cancer." (PMID 34948213, 2021). "CLDN6 therefore, might be a novel prognostic molecule for gastric cancer and a potential target candidate for future treatment of gastric cancer." (PMID 31827075, 2019). "Therefore, we explored the possible mechanism of CLDN6 in promoting the progression of gastric cancer." (PMID 31827075, 2019). "To investigate if CLDN6 could predict the survival of gastric cancer patients, we analyzed the data from GEO and TCGA databases as well as from Renji hospital." (PMID 31827075, 2019). "Thus in our study, the expression of claudin-2, and claudin-6 was down regulated in gastric cancer tissue while the expression of claudin-11 was up regulated." (PMID 23919729, 2013). "Our present data observes that claudin-2 and claudin-6 were both down-regulated and may be concurrently expressed in gastric cancer, reveals that claudin-2 and claudin-6 may act as synergistic tumor suppressors in gastric cancer." (PMID 23919729, 2013). "However, the role of CLDN6 in the malignant transformation of gastric cancer through the EMT network is still unknown." (PMID 31827075, 2019). "In this study, the gastric cancer patients with high expression of CTLA4 and ENTPD2 had a better survival prognosis, with high expression of CLDN6, EMB, GPR15, VWF and AKR1B1 suggesting poor prognosis, which was consistent with previous studies." (PMID 37066015, 2023). "The relationship between CLDN protein and the Hippo proteins has been reported; CLDN6 activates YAP and induces EMT by binding to LATS and inhibiting YAP suppression in gastric cancer cells." (PMID 32481659, 2020). "In addition, claudin-2 and claudin-6 may be concurrently expressed in gastric cancer." (PMID 23919729, 2013). "But for H. pylori-induced gastric cancer, there is no information regarding what transcription factors induce/upregulate the expression of CLDN6." (PMID 37762277, 2023). "In gastric cancer induced by Helicobacter pylori (H. pylori) there is no information regarding what transcription factors induce/upregulate the expression of CLDN6." (PMID 37762277, 2023).
gastric cancer (continued). "Additionally, CLDN6 interacts with LATS1/2 to reduce LATS1/2 and YAP1 phosphorylation, influence YAP1 entry into the nucleus, and enhance the invasive ability of gastric cancer cells." (PMID 36620607, 2022). "In MKN28 and AGS cell lines, western blot assay showed that p-LATS and p-YAP1 levels were increased significantly in the sh-CLDN6 group.The increased levels of p-YAP1 led to decreased YAP1 entry into the nucleus, thereby inhibiting the development of gastric cancer." (PMID 31827075, 2019). "The present work infers that the expression altered of claudin-2, claudin-6, and claudin-11 between human gastric cancers and adjacent non-neoplastic tissues and does not correlate with their clinical behavior." (PMID 23919729, 2013). "Through the intersection of differentially expressed genes (DEGs) that are highly expressed in gastric cancer tissues with those DEGs highly expressed in early-stage (T1) gastric cancer tissues exhibiting LNM, and with prognostic genes, we identified two biomarkers: HAVCR1 and Claudin 6 (CLDN6)." (PMID 40406257, 2025). "CLDN6 only exists in human embryonic cells and is not expressed in normal adult tissues; however, it is specifically expressed in various tumor tissues, such as gastric cancer, ovarian cancer, colon cancer, and germ cell carcinoma." (PMID 39915118, 2025). "There is no uniform conclusion on the expression of CLDN6 in gastric cancer tissues." (PMID 40687428, 2025). "However, in gastric cancer, in cells such as AGS, MKN7 and NUGC-3, CLDN6 silencing contributes to cell cycle arrest at the G1-S checkpoint through increasing p21WAF1/Cip1 and p27Kip1 and decreasing S-phase kinase-associated protein 2 (SKP2) protein levels, which are well-known cell cycle regulators." (PMID 36362009, 2022).
ovarian carcinoma (28 papers, 2013 to 2026). A malignant neoplasm originating from the surface ovarian epithelium. "Stadler and colleagues constructed mRNA encoding bispecific antibodies that directly targeted CD3 and ovarian carcinoma-associated antigen claudin 6 (CLDN6) and eliminated OV-90 cancer cells upon consecutive injection of a polymer/lipid-based transfection reagent carrying CD3 × CLDN6 mRNA." (PMID 40821123, 2025). "After correlation adjustment by purity, CLDN6 expression was negatively correlated with most gene markers of dendritic cells, M1 macrophages, monocytes, NK cells, and tumor-associated macrophages (TAMs) in ovarian cancer." (PMID 34249076, 2021). "In vitro-cultured ovarian cancer cell lines showed reversible changes in CLDN6 expression depending on cell density, accompanied by alterations in epithelial-mesenchymal transition (EMT)-related and stemness-related genes." (PMID 41628300, 2026). "In this study, we investigated the biological characteristics of CLDN6-positive EOC to identify its significance as a therapeutic target for ovarian cancer treatment." (PMID 41628300, 2026). "On the basis of promising clinical activities in the NCT05103683 clinical trial, a registry phase II clinical trial of ixotatug vedotin for the treatment of CLDN6-positive platinum-resistant epithelial ovarian cancer is ongoing (CATALINA-2 study, NCT06690775)." (PMID 41164107, 2025). "CLDN6 is another compelling target – being an oncofetal antigen, it is targeted by CAR T-cell therapies currently in early-phase trials (for ovarian cancer and other CLDN6+ solid tumors)." (PMID 40687428, 2025). "IMAB027, a humanized monoclonal antibody targeting CLDN6, has been evaluated in clinical trials for ovarian cancer (NCT02054351) and refractory germ cell tumors (NCT03760081)." (PMID 39915118, 2025). "In patients with CLDN6-positive ovarian cancer, the response rate (ORR) reached 67% at the dose of 2.4 mg/kg and 50% at 3.0 mg/kg." (PMID 40722601, 2025). "The ability of CLDN6-CAR NK cells to kill CLDN6-positive ovarian cancer cells were evaluated in vitro and in vivo by live cell imaging and bioluminescence imaging." (PMID 38481806, 2024). "RT-PCR analysis showed that CLDN6 mRNA had different transcriptional levels in seven human ovarian cancer cell lines, and the expression levels of SK-OV-3, A2780 and Hey were higher." (PMID 38481806, 2024). "Claudin-6 is a cell surface membrane protein that is highly expressed in various solid tumors, such as ovarian cancer, testicular cancer and endometrial cancer." (PMID 38481806, 2024). "In this study, immunohistochemistry and western blot assays demonstrated that CLDN6 was significantly upregulated in ovarian cancer tissues and a variety of ovarian cancer cell lines and localized in cell membranes." (PMID 38481806, 2024). "We performed immunohistochemical staining for CLDN6 in 62 cases of primary OC samples and found that 87.1% (54/62) of ovarian cancer tissues showed positive expression of CLDN6 and localized to the cell membrane." (PMID 38481806, 2024). "In this study, a human ovarian cancer cell line was used to construct subcutaneous tumors to verify the efficacy of CLDN6-targeted CAR NK cells." (PMID 38481806, 2024). "Other efforts have purified T cell receptor (TCR) genes from both CD4+ (DR4) and CD8+ (A2) T cells specific to CLDN6 that were obtained from a patient with ovarian cancer." (PMID 38371623, 2024). "Collectively, these results indicate that CLDN6 expression is upregulated in both OC primary tissues and cell lines and CLDN6 can be used as an ideal target for ovarian cancer treatment." (PMID 38481806, 2024). "According to our DE criteria (FC ≥ 20), we consider CLDN6 a strictly tumor-specific target for ovarian cancer patients." (PMID 37026005, 2023).